INS (insulin)
Diseases named in the same sentence as INS in open-access papers (continued):
Sharing a sentence is not in itself a finding about the gene and the disease.
type 2 diabetes (continued). "In a randomized study where 61 patients with type 2 diabetes were followed up over 24 months and diastolic myocardial dysfunction (E′), intima media thickness and arterial stiffness were significantly higher in patients receiving only conventional insulin therapy (human insulin b.d.)vs." (PMID 31929794, 2019). "Indeed, a Prudent diet composed of whole foods elicits fewer adverse health effects with better adherence than highly restrictive ketogenic diets, which has been shown to be effective in regulating insulin sensitivity in type 2 diabetes and pre-diabetic patients." (PMID 31600930, 2019). "The major difference suggested was that in type 1 diabetes, insulin deficiency seems to be the main factor for increased tau phosphorylation, while in type 2 diabetes, hyperglycemia-induced tau cleavage with contributing insulin disturbances may lead to major tau pathology." (PMID 31428627, 2019). "Type 2 diabetes (T2D) is characterized by a progressive defect in insulin secretion in the setting of relative insulin resistance." (PMID 31213603, 2019). "Type 2 diabetes mellitus (T2DM) is a growing, worldwide epidemic characterized as abnormal insulin secretion by pancreatic β-cells and peripheral insulin resistance, resulting in high blood glucose." (PMID 31304066, 2019). "Improvements in muscle quality may also reduce the risk of type 2 diabetes in older individuals because IMF content has a negative effect on insulin sensitivity." (PMID 30473735, 2018). "Our decision to adhere to the previously used DAWN2 definitions of type 1 and type 2 diabetes based on age of diagnosis, insulin use shortly after diagnosis, and current insulin use may have safeguarded against some of the biases inherent to self- or proxy report." (PMID 29347915, 2018). "In many of these individuals initial hyperinsulinemia is followed by later reduction of insulin secretion and development of type 2 diabetes mellitus (T2DM)." (PMID 30134843, 2018). "Lack of early insulin secretion is a classic deficiency of type II diabetes and may lead to high FBG concentrations and postprandial hyperglycemia." (PMID 30131712, 2018). "First, type 2 diabetes is a heterogeneous disease in both pathogenesis and clinical manifestation, thus a high HbA1c at baseline and at follow-up could be due to decreased insulin sensitivity, secretion and β-cell dysfunction." (PMID 29405097, 2018). "In this study, we observed that the UACR was also reduced in type 2 diabetics after two weeks of treatment, which indicates that insulin intensive treatment could ameliorate micro-albuminuria, which may be partially related to the reduction of the expression of MCP-1 and NF-κB." (PMID 29641741, 2018). "Obesity and type 2 diabetes may be defined as accumulation of excessive body fat that impairs health and longevity and as a chronic metabolic disorder that results partly in the inability of the body to respond adequately to circulating insulin, respectively." (PMID 29449830, 2018). "Therefore, GLP-1-RAs are more effective than conventional sulfonylurea drugs and glinide drugs (conventional insulin secretagogues) for treating type 2 diabetes, in which hypoglycemia and increased body weight are less likely to occur and in which insulin secretion is reduced." (PMID 29946474, 2018). "Additional studies may therefore be warranted to confirm whether a lack of effect on post-prandial glucose levels is also observed in type 1 diabetic subjects or those with type 2 diabetes who use insulin and whether this effect holds true for all varieties of date palm fruit." (PMID 29293579, 2018). "However, injectable medications other than insulin are increasingly used to treat type 2 diabetes." (PMID 30294713, 2018).
type 2 diabetes (continued). "However, in the 52-week extension trial dual action of liraglutide and insulin degludec in type 2 diabetes (DUAL I), the authors studied the fluctuations in plasma glucose of the combination of insulin degludec and liraglutide (IDegLira) against each of its components separately." (PMID 29805980, 2018). "Self-management forms a crucial part of type 2 diabetes (T2DM) treatment, especially for insulin treated individuals." (PMID 30348142, 2018). "Thus, it is important to examine whether HIIT/SIT protocols, with fewer and shorter high-intensity efforts, remain efficacious for improving insulin sensitivity and glycaemic control in type 2 diabetes." (PMID 30171349, 2018). "However, most of the current treatment options in type 2 diabetes and prediabetes target mainly the symptoms rather than insulin sensitivity and adipose tissue metabolism as causative factors." (PMID 29973382, 2018). "The aim of the study was to investigate ectopic fat deposition and insulin sensitivity, in a parallel single-blinded randomised controlled trial, comparing Paleolithic diet alone with the combination of Paleolithic diet and exercise in individuals with type 2 diabetes." (PMID 29696296, 2018). "Clinical benefits of FGM use, in particular a reduction in hypoglycemia, have also been reported in patients with type 2 diabetes mellitus (T2DM) on intensive insulin therapy." (PMID 30060632, 2018). "In this study, the annual incidence of severe hypoglycaemia episodes in insulin-treated type 2 diabetes was observed to be less than half of that in type 1 diabetes (1.15 events per person per year in type 1 diabetes vs 0.35 events per person per year in type 2 diabetes)." (PMID 28660491, 2018). "However, the pathogenesis of type 2 diabetes is different in youth versus adult patients, with younger patients tending to be insulin deficient rather than insulin resistant." (PMID 30446513, 2018). "The present finding that ICV injection of insulin promotes oxytocin secretion suggest that insulin resistance in oxytocin neurons could serve as a factor that leads to the reduction in oxytocin concentrations in obese and/or type 2 diabetic patients." (PMID 29991705, 2018). "However, only a few percent of native Swedes had a high familial burden of type 2 diabetes and our data were not powered to detect significant differences across ethnicities in the association between familial burden and insulin action." (PMID 29274011, 2018). "It has been well established that exercise intervention can improve insulin action and glycaemic control in individuals with type 2 diabetes that may be the result of an improved oxidative capacity of skeletal muscle that can lead to an improvement in β-cell function." (PMID 30199540, 2018). "However, the associations between ceramide levels and insulin sensitivity and the risk of type 2 diabetes are not consistent." (PMID 29751643, 2018). "Type 2 diabetes mellitus (T2DM) leads to hyperglycemia, one of the reasons is insufficient insulin production." (PMID 30542284, 2018). "We raise the next logical question of whether ß-Cell dysfunction in Type 2 Diabetes is due to impaired function, defined as failure, or if chronic overstimulation of the ß-Cell that exceeds its capacity to synthesize and secrete insulin, defined as abuse, is the main abnormality in Type 2 Diabetes." (PMID 30271382, 2018). "Fasting until lunchtime, as in the current study, has previously been shown to trigger increased postprandial hyperglycemia and impaired insulin response after lunch in type 2 diabetes, indicating that these findings may have particular relevance to those who skip breakfast." (PMID 29342865, 2018). "Fakhoury W, Lockhart I, Kotchie RW, Aagren M, LeReun C. Indirect comparison of once daily insulin detemir and glargine in reducing weight gain and hypoglycaemic episodes when administered in addition to conventional oral anti-diabetic therapy in patients with type-2 diabetes." (PMID 29527102, 2018).
type 2 diabetes (continued). "For example, the incidence of tendinopathy is increased in individuals with obesity and decreased insulin sensitivity, as seen in patients with type 1 and type 2 diabetes mellitus (T1/T2DM)." (PMID 30518382, 2018). "In this study, we have investigated the role of receptor trafficking in glucagon-like peptide-1 receptor (GLP-1R) agonism, an important treatment modality for type 2 diabetes (T2D) which improves pancreatic beta cell function and insulin sensitivity." (PMID 29686402, 2018). "Indeed, since type 2 diabetes results in part from insulin resistance, treating obesity would increase insulin sensitivity and lead to a remission of type 2 diabetes, especially with the emerging concept of adipose tissue targeting to treat obesity-associated diabetes with increased clinical hopes." (PMID 30463389, 2018). "Therefore, in addition to promoting the release of insulin, the improvement of the oxidative stress of pancreatic β-cells in type 2 diabetes by long-term treatment with tigerinin-1R peptides could be expected." (PMID 29360748, 2018). "Furthermore, this is the first attempt to demonstrate enzyme kinetics and simulate molecular docking of 1–3 against these two enzymes, and demonstrate glucose uptake activity in insulin-resistant HepG2 cells which is worthwhile to explore the pharmacological mechanism of M. alba in type II diabetes." (PMID 29786669, 2018). "The pathophysiology of type 2 diabetes mellitus (T2DM) involves insulin resistance and impaired insulin secretion." (PMID 30028879, 2018). "Metabolic Syndrome (MetS) and Type 2 diabetes (T2D) are clinical conditions involving the impaired uptake and utilization of glucose, altered lipid metabolism, and the disruption of the metabolic signaling pathways that regulate insulin secretion from pancreas." (PMID 30687238, 2018). "It was estimated that approximately 90% DM were type 2 diabetes mellitus (T2DM), which occurs due to cells developing a resistance to insulin." (PMID 29981194, 2018). "The thiazolidinediones (TZDs) are synthetic activators of PPARγ that induce insulin sensitization as a treatment for type 2 diabetes mellitus (T2DM)." (PMID 30008738, 2018). "Therefore, we speculated that the role of PCSK9 in the progression of type 2 diabetes and metabolic disorders could be mediated by insulin." (PMID 29343301, 2018). "However, only ASE associated with exercise training reduced TNF-α serum levels in type 2 diabetic rats, which may contribute to the improvement of insulin sensitivity." (PMID 29920546, 2018). "Obesity is the main factor that induces type-2 diabetes (T2DM), and may cause a proinflammatory state accompanied by the increase in oxidative stress, which may interfere with the anti-inflammatory effects of insulin." (PMID 30320140, 2018). "Insulin has been considered as a therapy option of last resort in type 2 diabetes (T2DM) management." (PMID 29904712, 2018). "Because modulation of LPL activity in oxidative tissues affects free fatty acid delivery, and thereby nutrient partitioning and insulin sensitivity, endogenous regulators of LPL activity may impact glucose homeostasis and risk for development of type 2 diabetes." (PMID 29899519, 2018). "BG levels could be finely controlled by insulin, and the abnormal concentration of BG is caused by the absence of insulin secretion (type I diabetes, T1D) or defective insulin secretion and action (type II diabetes, T2D)." (PMID 28106820, 2017). "This study examined appropriate insulin level in selecting animal model for type 2 diabetes (T2D) studies." (PMID 28129400, 2017). "Different from type 2 diabetes, type 1 diabetes (T1D) is recognized as an autoimmune disorder in which the insulin-producing β-cells in the Langerhans islets within the pancreas are the target of T cell-mediated destruction, resulting in lifelong dependence upon exogenous insulin." (PMID 29410963, 2017).
type 2 diabetes (continued). "Despite the increase in the absolute number of events, the incidence rate of severe hypoglycemia in people with insulin-treated type 2 diabetes requiring emergency medical treatment was significantly lower and may have been promoted by changes in clinical management." (PMID 28824815, 2017). "Our results indicated that curcumin with the ability in adjusting lipid profile and increasing the sensitivity to insulin due to presence of flavonoid may be considered as a natural effective compound to improve some metabolic syndrome in patients with diabetes type 2, and/or PCOS." (PMID 28836404, 2017). "Interestingly, the concomitant increase in insulin and Aβ levels may lead to redistribution of available IDE away from its function as an Aβ-degrading enzyme, which is why patients with type II diabetes have an increased risk of AD." (PMID 28719622, 2017). "The UKPDS analyzed 5102 recently diagnosed type 2 diabetes patients followed up from 1977 to 1997 and found that intensive glycemic control with sulfonylurea or insulin therapy decreases progression of microvascular disease and may also reduce the risk of heart attacks." (PMID 28725272, 2017). "Notably, Israeli and Turkish cohorts are more likely to have hyperinsulinemia and can develop type 2 diabetes later in life, while Ecuadorian cohorts have improved measures of glucose homeostasis, including improved insulin sensitivity and resistance to type 2 diabetes." (PMID 28933734, 2017). "Furthermore, patients with type 2 diabetes who are insulin-dependent tend to be less well-controlled than type 2 patients who are being managed with oral hypoglycemics only, and may be more likely to return to the ED more often." (PMID 28702883, 2017). "In conclusion, the present study showed that administration of SeP-neutralizing Ab could improve, at least in KKAy mice model, glucose metabolism, insulin resistance and insulin secretion in vivo, and suggested a strategy of targeting SeP for treatment of type 2 diabetes." (PMID 29162828, 2017). "By comparison with the period of June 1997 to May 1998, significantly lower incidence were observed in people with type 1 diabetes (IRR = 0.720, 95% CI: 0.580–0.892, p < 0.001) and people with type 2 diabetes receiving insulin (IRR = 0.314, 95% CI: 0.249–0.395, p = 0.008)." (PMID 28824815, 2017). "Type 2 diabetes (T2D) is a metabolic disorder characterized by chronic insulin resistance and loss of functional pancreatic β-cells due to relative (rather than absolute) deficiency of insulin." (PMID 28176546, 2017). "Type 2 diabetes mellitus (T2DM), characterized by persistent hyperglycemia, is a chronic metabolic disorder resulting from defects in insulin secretion and/or its action." (PMID 28558824, 2017). "Frequently, the perceived link between diet and type 2 diabetes is through excess energy intake that leads to obesity, and over-consumption of refined carbohydrates that rapidly raises blood glucose and places a compensatory demand on the beta cells for endogenous insulin." (PMID 28124081, 2017). "Furthermore, high RBP4 levels have been observed in obese subjects, type 2 diabetic patients, adolescents with cardiovascular risk factors, and nonobese individuals low insulin sensitivity suggesting a pathogenic link between RBP4 and IR in humans." (PMID 29333450, 2017). "Thus, we asked whether genetic variation in the DPP4 gene affects incretin levels, insulin secretion, and glucose tolerance in participants of the TÜbingen Family study for type-2 diabetes (TÜF)." (PMID 28750074, 2017). "For insulin, fasting plasma insulin/glucose ratios are the only non-invasive approach to determine insulin sensitivity, and classification of risk of type 2 diabetes could be enhanced by additional biomarkers." (PMID 28904371, 2017).
type 2 diabetes (continued). "More importantly, this approach could be used to quantify the combined effects of exercise and meal on glucose homeostasis regulation, hence favoring the definition of a tailored exercise-based intervention in the control of insulin secretion for the treatment of type 2 diabetes." (PMID 28704555, 2017). "Over time, persistent elevated insulin secretion can no longer be maintained by pancreatic beta-cells, leading to chronic hyperglycemia and the associated diagnoses of prediabetes or type 2 diabetes, which significantly increases the risk for cardiovascular disease and mortality." (PMID 29099048, 2017). "Type 2 diabetes mellitus (T2D) is a metabolic disorder which is characterised by insulin resistance, defective insulin secretion or both." (PMID 28091589, 2017). "Moreover, we have identified crucial factors necessary for improved survival, induction of hyperglycemia and sustained diabetic glucose intolerance using a combination of HFHC diet and STZ in the guinea pig to yield a reproducible model of insulin-independent overt type 2 diabetes." (PMID 28093504, 2017). "In type 2 diabetes (T2D), impaired insulin signaling leads to hyperglycemia and long-term complications, including metabolic liver dysfunction, resulting in non-alcoholic fatty liver disease (NAFLD)." (PMID 29104232, 2017). "PPARγ ligands glitazones (rosiglitazone and pioglitazone) are deemed as insulin sensitizer to improve the symptoms of patients with Type 2 diabetes mellitus (T2DM)." (PMID 28186999, 2017). "Moreover, Grb14 expression is increased in adipose tissue of insulin-resistant animal models and type 2 diabetic patients, and improvement of insulin sensitivity in ob/ob mice by treatment with an antidiabetic drug (thiazolidinedione) is associated with a reduction in Grb14 expression." (PMID 29203791, 2017). "Similarly, in insulin-treated patients with type 2 diabetes mellitus (T2DM), a recently randomized trial was analyzed in according with SPIKE study, and the results showed that sitagliptin treatment could regress carotid IMT." (PMID 28619058, 2017). "Therefore, reducing the sitting time may improve glycaemic control and insulin sensitivity in type 2 diabetes." (PMID 27904925, 2017). "Type 2 diabetes mellitus (T2DM) is a chronic metabolic disorder characterized by an inability to produce and/or utilize adequate amounts of the hormone insulin." (PMID 29065911, 2017). "CLW improved insulin signaling and it prevented the loss of bodyweight in non-obese type 2 diabetic rats, although it may protect against weight gain in obese type 2 diabetes, thereby by leading to normoinsulinemia." (PMID 29104217, 2017). "Moreover, we found that age at natural menopause was associated with type 2 diabetes independent of glucose and insulin levels." (PMID 28721436, 2017). "Not only regular breakfast omission is associated with obesity, CVD, and type 2 diabetes but an appropriate breakfast should contain a blend of macronutrients minimizing insulin excursions and ghrelin levels to foster a hormone milieu not predisposing to obesity." (PMID 28706955, 2017). "Current therapeutic strategies for type 2 diabetes are limited and involve insulin and oral antidiabetic agents that stimulate pancreatic insulin secretion, reduce hepatic glucose production, delay digestion and absorption of intestinal carbohydrates, or improve insulin action." (PMID 28085064, 2017). "From June 1997 to May 1998, among the 7678 people with type 2 diabetes, 901 (11.7%) were being treated with insulin, 2823 (36.8%) were being treated with sulfonylureas (group b), and 3954 (51.5%) were being treated with non-insulin secretagogues alone (group a)." (PMID 28824815, 2017). "Adiponectin and its signaling through the receptors AdipoR1 and AdipoR2 rank highly in the ongoing search for the holy grail that might improve insulin sensitivity, modulating inflammatory responses, and regulating energy metabolism in patients with obesity and/or Type 2 Diabetes (T2D)." (PMID 28271029, 2017).